PCSK9 (proprotein convertase subtilisin/kexin type 9)
Diseases named in the same sentence as PCSK9 in open-access papers (continued):
Sharing a sentence is not in itself a finding about the gene and the disease.
diabetes (continued). "Second, the safety and tolerability of PCSK9 inhibition and anti-PD-1/PD-L1 immunotherapy need to be evaluated, especially in patients with cardiovascular diseases, diabetes, or other comorbidities." (PMID 39324018, 2024). "A meta-analysis linking PCSK9 LOF variants and diabetes risk demonstrated the correlation between decreased LDL-C and increased risk of diabetes, with an odds ratio of 1.19 (95% confidence interval 1.02–1.38) for each 1 mmol/L decrease in LDL-C." (PMID 39139638, 2024). "Future longitudinal studies would be important in further delineating the relationship between maternal obesity or diabetes and infant PCSK9 levels." (PMID 38440108, 2024). "For instance, in the ODYSSEY OUTCOMES trial, patients with diabetes experienced a substantial reduction in MACEs when treated with PCSK9 inhibitors in combination with statins, demonstrating notable absolute risk reductions." (PMID 39539858, 2024). "According to these findings, anti-PCSK9 medications, which primarily target circulating Pcsk9, have only a minimal influence on the malfunction of β-cell s and the prevalence of diabetes." (PMID 36936164, 2023). "In this review, We focus on the feeding-induced hepatokines, including Adropin, Manf, Leap2 and Pcsk9, Which participate in the occurrence and development of diabetes." (PMID 36936164, 2023). "Studies of statins combined with cholesterol absorption inhibitors or/and PCSK9 monoclonal antibodies have shown that ASCVD patients with comorbid diabetes benefit more from intensive lipid lowering." (PMID 37711173, 2023). "In line with this evidence, among patients with ST-segment elevation myocardial infarction undergoing PCI, those with high PCSK9 levels and diabetes mellitus had the lowest cumulative event-free survival rate." (PMID 37620933, 2023). "Although, PCSK9-Abs were not related with serum lipid levels, it is very intriguing that PCSK9-Abs were increased in the patient with diabetes." (PMID 37012310, 2023). "Previous studies have shown that insulin resistance and subsequent hyperinsulinemia can enhance plasma circulating PCSK9 levels, and that the increase in plasma PCSK9 levels is related to poor glycemic control in patients with diabetes." (PMID 38115042, 2023). "Überzeugende Daten zeigen, dass eine medikamentöse Therapie mit Statinen, Ezetimibe und PCSK9 Hemmern das kardiovaskuläre Risiko von Patienten mit Diabetes senken kann." (PMID 37101037, 2023). "We assessed the relative risk for all treatment-related adverse events, serious adverse events, diabetes-related adverse events, and neurocognitive and neurologic adverse events with PCSK9 inhibitors compared to controls (placebo or ezetimibe)." (PMID 36704607, 2023). "After measuring PCSK9-Abs in the blood of patients with diabetes, they were followed up for an observational period of 4.93 years (mean: 4.93 years, SD: 2.77 years, max: 9.58 years, min: 0.07 years)." (PMID 37012310, 2023). "Owing to the close relationship between lipid and glucose metabolism, an increasing number of studies have found a close relationship between PCSK9 and diabetes." (PMID 38115042, 2023). "Existing epidemiological and clinical research results have shown that PCSK9 levels are high in patients with diabetes." (PMID 38115042, 2023). "When participants were categorized into 4 subgroups according to PCSK9 levels and diabetes status, high PCSK9 levels plus diabetes subgroup had the lowest cumulative event-free survival rate (P = 0.043)." (PMID 35596184, 2022). "The strength of the correlation between plasma PCSK9 and NT-proBNP was likely greater in patients affected by type 2 diabetes mellitus (r = −0.483; p = 0.006) and in male patients (r = −0.431, p = 0.001)." (PMID 36009507, 2022). "There was an ascending gradient with regard to the proportions of women, CAD and diabetes; the baseline levels of age, BMI, systolic blood pressure, HbA1c and PCSK9; and the usage of antihypertensive drugs across NFS status (all P < 0.05)." (PMID 34996457, 2022).
diabetes (continued). "Real-world experience with PCSK9 inhibitors is still in its infancy, with neurocognitive adverse events and diabetes remaining debated long-term safety issues." (PMID 36383291, 2022). "Among factors that affect the expression of PCSK9 we can single out: age, gender, diet, aerobic exercises, pregnancy, diurnal rhythm, diseases of thyroid gland, kidneys and liver, type 2 diabetes mellitus (DM2), obesity, drugs (e.g., statins)." (PMID 35323699, 2022). "These 7 variables included PCSK9 R93C, and 6 variables (sex, hypertension, diabetes, hyperlipidemia, smoking, family history of premature CHD) that are traditional risk factors for CHD." (PMID 35480303, 2022). "Impairment of glycaemia is also variable in human carriers of PCSK9 LOF variants, where the diabetes risk correlates with the individual degree of functional loss." (PMID 36527064, 2022). "Compared with various statins and ezetimibe, PCSK9 inhibitors have shown a favorable safety profile in muscle-related events, cognitive impairment and diabetes." (PMID 36506552, 2022). "The addition of a PCSK9 targeted approach therapy to statin plus ezetimibe (preferably as an FDC) should be recommended in patients with diabetes who are required to reduce LDL-C by more than 80% from baseline." (PMID 36443827, 2022). "To understand the effect of anti-PCSK9 therapy on glycemic indices, we evaluated the preventive impact of the nanoliposomal anti-PCSK9 vaccine in rats with streptozotocin- (STZ-) induced diabetes." (PMID 34504898, 2021). "The relationship between plasma PCSK9 concentration and diabetes mellitus has been of note in some previous studies." (PMID 34380558, 2021). "In the present study, in addition to Pcsk9 levels, ApoB, creatine kinase, NT-proBnp, diabetes were also independent predictors of SYNTAX scores." (PMID 34044829, 2021). "Of note, due to refund claims by the Austrian health insurance only patients with sufficiently controlled diabetes (HbA1c < 64 mmol/mol (8.0%)) are eligible for PCSK9 inhibitor therapy." (PMID 33894772, 2021). "LDL‐cholesterol lowering variants that upregulate receptor uptake of LDL, such as in PCSK9 and HMGCR, are associated with diabetes via unclear mechanisms." (PMID 33527668, 2021). "In a Mendelian randomized study, four SNPs in or near PCSK9 were associated with a reduction in LDL-C and an increased risk of diabetes together with a higher circulating glucose concentration, body weight, and waist-to-hip ratio." (PMID 34940565, 2021). "The present findings call for additional studies in other experimental models of diabetes to confirm the positive impact of PCSK9 immunization on glycemic indices." (PMID 34504898, 2021). "The subjects of this study were newly diagnosed with PNS, and the influence of confounding factors such as diabetes and lipid-lowering drugs on the expression of PCSK9 were excluded." (PMID 32349585, 2020). "Although sensitivity analysis performed on confirmed cases was consistent with the original analysis, the PCSK9-diabetes relationship should also be exclusively analyzed using confirmed cases in future studies." (PMID 33302966, 2020). "Variants in these two genes were associated with very similar effects on the risk of diabetes: OR for each 10 mg per deciliter decrease in LDL-C cholesterol was 1.11 (95% CI, 1.04 to 1.19) for PCSK9 and 1.13 (95% CI, 1.06 to 1.20) for HMGCR." (PMID 32040442, 2020). "More intensive investigations are needed to clarify the precise mechanisms by which the PCSK9 pathway is involved in diabetes development." (PMID 33302966, 2020). "The problem of the increase in diabetes appears to be not only due to statin side effects, but are apparently shared with the new PCSK9." (PMID 30922303, 2019).
diabetes (continued). "We assess the selection performance of POINT using simulations and illustrate how it can be used to prioritize individual rare variants in PCSK9, ANGPTL4 and CETP in the Action to Control Cardiovascular Risk in Diabetes (ACCORD) clinical trial data." (PMID 30779729, 2019). "Our study indicates that polydatin ameliorates lipid and glucose metabolism in type 2 diabetes mellitus by downregulating PCSK9." (PMID 26833058, 2016). "Our results demonstrate that polydatin ameliorates lipid and glucose metabolism in type 2 diabetes mellitus by downregulating proprotein convertase subtilisin/kexin type 9 (PCSK9)." (PMID 26833058, 2016). "Nevertheless, the results of ongoing cardiovascular end-point trials are needed to determine the true effect of short term PCSK9 inhibition on diabetes risks." (PMID 27864787, 2016). "In a study of patients with diabetes, Cariou et al22 reported that PCSK9 rose by 32% on statin therapy, which destroyed the correlation between PCSK9 and LDL‐C." (PMID 23537802, 2013). "Individuals with loss-of-function PCSK9 mutations are healthy and do not show evidence of neurocognitive impairment, increased incidence of diabetes, cataracts, or stroke." (PMID 40630126, 2025). "Furthermore, in diabetes, PCSK9 suppressed the expression and activation of protein kinase B (AKT) and eNOS in endothelial cells." (PMID 39982361, 2025). "Furthermore, carriers of PCSK9 and insertion of insLEU within positions 15 to 21 of the signal peptide of PCSK9 showed also increased occurrence of prediabetes and diabetes status." (PMID 38907775, 2025). "Statins have been linked to insulin resistance and the subsequent development of diabetes; however, Inclisiran’s targeted mechanism offers a promising advantage by focusing on PCSK9, thereby bypassing multiple metabolic pathways and suggesting a lower risk of interference with glucose metabolism." (PMID 39857168, 2025). "Collectively, these observations suggest that while safety concerns warrant ongoing surveillance, current evidence does not indicate a substantial additional risk of diabetes or neurocognitive impairment when PCSK9 inhibitors are used on top of statins." (PMID 40969933, 2025). "Nonetheless, sex hormones might influence PCSK9 levels in post-menopausal women affected by diabetes and an increased prevalence of diabetes was observed in early-onset menopause patients compared to women in normal-onset menopause." (PMID 40144869, 2025). "Additionally, considering that PCSK9 promotes the clearance of oxidized LDL, subsequently increasing the synthesis of LDL receptors, the use of PCSK9 inhibitors can lower LDL concentrations in patients with diabetes." (PMID 41293421, 2025). "Indeed, several studies confirmed higher PCSK9 levels in patients with type 2 diabetes mellitus (T2DM) than the general population as well as in women than in men." (PMID 40144869, 2025). "At the same time, long-term administration of PCSK9 inhibitors (PCSK9i) has not been associated with a significant increase in incident diabetes." (PMID 41008547, 2025). "PCSK9 emerges as a key modulator of endothelial integrity in diabetes." (PMID 41008547, 2025). "In accordance with that, clinical treatment with PCSK-9 antibodies or ezetimibe reducing LDL-cholesterol extracellularly or by liver selective action, like bempedoic acid or inclisiran, were neutral regarding diabetes risk." (PMID 39775321, 2025). "Indeed, recent data indicates very high costs related to the use of SGLT2 inhibitors and GLP-1 receptor agonists among individuals with diabetes in particular, as well as for PCSK9 inhibitor therapy in the overall ASCVD population." (PMID 38978114, 2024).
diabetes (continued). "Recent evidence from a meta-analysis, which included eight large randomized controlled trials, showed that PCSK9 inhibitors effectively reduced the risk of major cardiovascular events (MACE) and improved lipid profiles in patients with diabetes and dyslipidaemia over a median follow-up of 51 weeks." (PMID 38757060, 2024). "Lastly, although not confirmed in randomized controlled trials, genomic data suggests that PCSK9 inhibitors (PCSK9i) lead to greater risk of diabetes, but not weight gain." (PMID 39302589, 2024). "This suggests that the roles of islet-derived PCSK9 and liver-derived PCSK9 in diabetes may differ, necessitating more research to uncover the underlying mechanisms." (PMID 39139638, 2024). "In patients with metabolic disturbances, the most optimal use is pitavastatin (that does not increase new onset diabetes or even has a potential to reduce the risk), ezetimibe, bempedoic acid, and a PCSK9 inhibitor/modulator." (PMID 38165521, 2024). "PCSK9 inhibitors do not increase the risk of diabetes (RR 0.99; 95% CI: 0.92–1.07) and same was true for ezetimibe (RR 1.05; 95% CI: 0.95–1.15)." (PMID 38988669, 2024). "So far, it has been noticed that inhibitors of PCSK9 do not increase the risk of diabetes or muscle pain and myopathy—as is the case with statin therapy." (PMID 36839644, 2023). "It should be noted, however, that completed clinical trials have not shown adverse effects of PCSK9 inhibitors on the risk of diabetes, but the safety of the inhibitors should be validated in long-term randomized trials." (PMID 36936164, 2023). "Currently, proprotein convertase subtilisin/kexin type 9 (PCSK9) inhibitors are a new class of drugs, which may benefit patients with high risk of atherosclerotic cardiovascular disease, such as diabetes mellitus." (PMID 37217967, 2023). "First, we included only patients with diabetes for further analysis, and whether PCSK9-Abs and survival prognosis are related in other groups, such as HDs, is unclear." (PMID 37012310, 2023). "Clinical trials and meta-analyses have shown that treatment with PCSK9 inhibitors does not increase the risk of incident diabetes mellitus." (PMID 37109734, 2023). "We therefore suggest that PCSK9-Ab levels may be used as a novel marker for the prognosis of patients with diabetes." (PMID 37012310, 2023). "The primary endpoint of this study was to examine whether PCSK9-Abs can be a prognostic marker for overall mortality among the patients with diabetes." (PMID 37012310, 2023). "Long-term risk of diabetes-related adverse events was assessed in 10 studies including 24,745 participants treated with PCSK9 inhibitors, and the incidence of diabetes-related adverse events was 4.50% (95% CI, 3.10%–6.50%), when applied the random-effects model." (PMID 36704607, 2023). "PCSK9-Abs may be a novel prognostic marker for overall mortality in patients with diabetes, and further studies are warranted to verify its usefulness." (PMID 37012310, 2023). "Therefore, it is recommended that patients at high risk of diabetes choose statins as the basic lipid-lowering therapy, and if LDL-C is not achieved, a combination of cholesterol absorption inhibitor or PCSK9 inhibitor is required." (PMID 37711173, 2023). "The inhibitors of proprotein convertase subtilisin/kexin type 9 (PCSK9) have emerged in the last years as potential alternatives to statins due to their high efficiency and safety without indications for a diabetes risk so far." (PMID 36527064, 2022). "Besides the evaluation of the relationship between PCSK9 inhibitors and the risk of NOD, it is of interest to understand the lag frame required to diabetes to manifest." (PMID 36383291, 2022). "The dependent variable was whether pregnant women were diagnosed with GDM, and the independent variables were age, gestational age, family history of diabetes, pre-BMI, abdominal girth, and PCSK9." (PMID 35498417, 2022).
diabetes (continued). "Acetate not only improved the hypothalamic-pituitary-ovarian function of female patients with T2DM by inhibiting histone deacetylase-5 (HDAC5), but also alleviated the testicular dysfunction in male patients with diabetes by inhibiting proprotein convertase subtilisin/kexin type 9 (PCSK9)." (PMID 35242721, 2022). "However, the role of PCSK9 in diabetes, especially with this type in transplant patients, is still unclear." (PMID 35683632, 2022). "Neither LDL-C lowering (38.7 mg/dL) nor the use of PCSK9 inhibitors was associated with the incidence of diabetes, respectively, risk ratio = 1.07 (95%CI 1.03–1.11) and risk ratio = 1.00 (95%CI 0.93–1.07)." (PMID 36383291, 2022). "Diabetes belonged to the exclusion criteria, and the question of whether the PCSK9 inhibitor affects hemostasis in diabetic patients remains open." (PMID 35566668, 2022). "If only a single lead SNV rs10788994 in the PCSK9 gene region was used as genetic instrument for reducing LDL-C, such as HMGCR rs3064191 alone, the effect size would be insufficient to increase the risk of diabetes." (PMID 36142332, 2022). "Therefore, it is essential to evaluate the impact of a newly developed PCSK9 inhibitor on glycemic indices and the progression of diabetes." (PMID 34504898, 2021). "To determine whether the polymorphisms of the PCSK9 gene were independent risk factors for CAD, we adjusted for confounding risk factors, including TGs, TC, HDL-C, LDL-C, and the prevalence of diabetes." (PMID 34075144, 2021). "Partial correlation corrected for age, BMI, liver steatosis, diabetes and LDL revealed significant associations of serum PCSK9 with the MELD score (r = −0.395, p = 0.031), bilirubin (r = −0.372, p = 0.043), leukocyte count (r = 0.521, p = 0.003) and CRP (r = −0.459, p = 0.011)." (PMID 33920491, 2021). "Hence, the safety and efficacy of PCSK9 inhibitors, especially those apart from mAbs, regarding the regulation of glycemic indices in diabetes require further investigations." (PMID 34504898, 2021). "Nevertheless, circulating, exogenous PCSK9 can mediate significant effects on cardiomyocytes, which could become increasingly important in conditions with increased PCSK9 blood release such as obesity or diabetes mellitus." (PMID 33643060, 2021). "Potential beneficial cardiovascular effects might be expected in patients with diabetes receiving both PCSK9 inhibitor therapy as lipid-lowering agent and SGLT2 inhibitors and/or GLP1-RA for diabetes management." (PMID 33894772, 2021). "The rs615563 variant of PCSK9 (a gain-of-function mutation) is associated with increased triglycerides and cholesterol levels, but its association with the incidence of diabetes is not well defined." (PMID 34380558, 2021). "The role of PCSK9 in glucose homeostasis and diabetes is still controversial." (PMID 33920491, 2021). "Moreover, miR-483-5p is associated with future onset of both diabetes and cardiovascular disease and increases hepatic LDL receptor levels by inhibiting PCSK9 production." (PMID 34084179, 2021). "The results indicated that a negative association with PCSK9 levels and PT remained significant after adjustment for age, gender, hypertension, diabetes mellitus, CAD, smoking status, BMI (β = − 0.189, p < 0.001)." (PMID 34809656, 2021). "It is conceivable that PCSK9 may impair EPC by modifying insulin secretion and metabolic control, or vice versa that the metabolic derangement of diabetes may alter PCSK9 levels, in turn affecting EPC number." (PMID 33958634, 2021). "We did not replicate the increased risk of diabetes seen in other studies examining pleiotropy of PCSK9 LoF." (PMID 33166319, 2020). "Furthermore, we compared metabolic parameters according to the PCSK9 quartile group among the participants who developed diabetes." (PMID 33302966, 2020). "Further studies about the role of the gut microbiota in the PCSK9-diabetes relationship are needed." (PMID 33302966, 2020).